MED19 (mediator complex subunit 19)
Diseases named in the same sentence as MED19 in open-access papers (continued):
Sharing a sentence is not in itself a finding about the gene and the disease.
cancer (13 papers, 2013 to 2025). A tumor composed of atypical neoplastic, often pleomorphic cells that invade other tissues. "In 2003, MED19, or lung cancer metastasis-associated protein 1, was cloned from lung large carcinoma and found to be an important part of the Mediator complex." (PMID 35047403, 2021). "Med19 has been implicated in the progress of several cancers, and knockdown of its expression may inhibit the progression of these cancers." (PMID 28125713, 2017). "Early-stage cancers exhibit higher canonical MED19 expression than alternative MED19, consistent with canonical MED19’s ability to promote cell proliferation under androgen deprivation." (PMID 37880276, 2023). "While alternative MED19 is present in most cancers, it is typically expressed at lower levels compared to canonical MED19." (PMID 37880276, 2023). "We next investigated the expression of MED19 protein isoforms in various stages of prostate development and cancer using immunohistochemistry (IHC)." (PMID 37880276, 2023). "MED19 has been demonstrated to impact cancer cell characteristics, including growth and mobility, across numerous cancers, including prostate cancer." (PMID 37880276, 2023). "MED19 is proposed to be involved in cancer growth, and its expression inhibits the spread and growth of cancers." (PMID 35615285, 2022). "Further, several studies have shown that MED19 plays a key role in malignant tumor growth by regulating signals related to cell growth, differentiation, cell cycle, and apoptosis." (PMID 35047403, 2021). "Numerous studies have shown that MED19 plays a role in tumor growth, migration, invasion, and apoptosis of various cancer types." (PMID 35047403, 2021). "By reducing the expression of MED1/17 and MED19, the growth and proliferation of cancer cells were inhibited." (PMID 34649520, 2021). "In addition, within the clinical specimens collected, MED19 was highly expressed in cancer tissues compared with paracancerous tissues." (PMID 35047403, 2021). "Med19 has been reported in the progress of several cancers, and knockdown of its expression may inhibit the growth and spread of these cancers." (PMID 28125713, 2017). "Mediator Complex Subunit 19 (Med19) is overexpressed and plays promotional roles in many cancers." (PMID 28125713, 2017). "However, the mechanism Med19 interacts with other signalling pathways leads to cancer development remains poorly understood, and further investigation is needed to determine the function of Med19 in BCa initiation and progression." (PMID 28631286, 2017). "Our study may also have implications for MED19 function in other cancers." (PMID 33513133, 2021). "The close relationship between tumorigenesis among multiple cancer types and numerous mediator complex subunits including MED1, MED12, MED16, and MED19 has been extensively reported." (PMID 35558516, 2022).
tumor (12 papers, 2011 to 2024). "MED19 was upregulated in HCC tissues compared with tumor-adjacent tissues, and was associated with a poor prognosis." (PMID 35047403, 2021). "On the one hand, the mechanism of MED19 in tumor chemotherapy resistance and autophagy remains to be further explored." (PMID 39462350, 2024). "We also performed immunohistochemistry (IHC) to examine MED19 isoform expression in vivo during tumor development." (PMID 37880276, 2023). "Based on the GEPIA dataset, matching TCGA normal and GTEx data, MED19 expression was found to be significantly higher in HCC tissues relative to other non-tumor tissues." (PMID 35047403, 2021). "As a member of the Mediator complex, MED19 plays a key role in the activation and inhibition of tumor signal transduction and transcriptional regulation and has a role in the induction of other developmental diseases." (PMID 35047403, 2021). "Thirty days later, tumours were harvested, and measurement of tumour volume showed that knocking‐down of Med19 protein leads to lower tumour volume (both P < 0.05) and reduced tumour weight compared to control groups (both P < 0.01)." (PMID 28631286, 2017). "Further, RNAi-mediated knock-down of Med19 in cultured human tumor cells can reduce proliferation, and tumorigenicity when injected into nude mice." (PMID 24786462, 2014). "Further efforts and investigations are needed to clarify the tumor-promoting mechanism of MED19." (PMID 35047403, 2021). "However, the staining of Med19 was moderate in low‐grade tumour tissues and strong in high‐grade ones." (PMID 28631286, 2017). "For the mechanism, we found Med19 could regulate the expression of multiple genes relevant to tumor growth and metastasis, including P27, pAKT, pPI3K, IGF1R, E-Cadherin, N-Cadherin, Vimentin, ZEB2, Snail-1 and Snail-2." (PMID 28125713, 2017). "Furthermore, IHC analysis showed that down‐regulation of Med19 suppressed the expression of proliferation marker Ki‐67 in tumour tissues compared with control shRNA‐treated groups." (PMID 28631286, 2017). "Med19 also plays an important role in tumour formation and progression." (PMID 28631286, 2017). "To further explore the tumor inhibited ability of Med19 shRNA, we used a xenograft model to examine whether Med19 shRNA inhibited tumor growth in vivo." (PMID 23705783, 2013). "Additionally, MED19 was correlated with tumor immune infiltration." (PMID 35047403, 2021). "Therefore, we further performed experiments to test whether Med19 subunit in Mediator plays an important role in BCa cell growth and tumour metastasis via regulating Wnt/β‐catenin signalling pathway." (PMID 28631286, 2017). "The level of MED19 transcription was significantly higher in HCC patients relative to healthy subjects in the subgroup analysis based on gender, age, race, tumor grade, etc.." (PMID 35047403, 2021). "Upregulation of tumor promoting genes in the PD-L1 positive group were notable for CD68, MED19 and CD46." (PMID 33415077, 2020). "PD-L1 expression positively correlated with high expression levels of tumor promoting genes such as CD68, ADAM12, FXYD5, S100A11, CD46, and MED19 (and ST1D)." (PMID 33415077, 2020). "Functional assays showed that knocking‐down of Med19 can suppress cell proliferation and migration in T24, UM‐UC3 cells and 5637 in vitro, and inhibited BCa tumour growth in vivo." (PMID 28631286, 2017). "First, we analyzed the expression patterns of MED19 in different tumor and non-tumor tissues." (PMID 35047403, 2021).
infection (2 papers, 2013 to 2020). The state of being infected such as from the introduction of a foreign agent such as serum, vaccine, antigenic substance or organism. "Only the Med19 RNAi line displayed sensitivity to Ecc15 infection." (PMID 33746938, 2020).
MED19 also shares sentences with these, for which no sentence is quoted: melanoma (4 papers); colorectal cancer (2); glioma (2); hepatocellular carcinoma (2); large cell lung cancer (2); lung adenocarcinoma (2); schizophrenia (2); autoimmune thyroid disease (1); bowel cancer (1); lentivirus infection (1); liver cancer (1); lung squamous cell carcinoma (1); lymph node metastasis (1); non-small cell lung carcinoma (1); ovarian carcinoma (1); pancreatic cancer (1); prostate tumors (1); psychiatric disorder (1).